RGS2 (regulator of G protein signaling 2)
Diseases named in the same sentence as RGS2 in open-access papers (continued):
Sharing a sentence is not in itself a finding about the gene and the disease.
prostate carcinoma (16 papers, 2010 to 2024). A carcinoma that arises from epithelial cells of the prostate gland. "During the progression of prostate cancer, the downregulation of RGS2 expression is associated with hypoxia and is related to the regulation and influence of tumor phenotypes." (PMID 39132501, 2024). "For example, overexpression of RGS1 inhibited CXCL12-mediated human plasmacytoma cell migration, and epigenetic inhibition of RGS2 has been associated with prostate cancer progression and overexpression of RGS5 on lung cancer cells." (PMID 35646090, 2022). "Furthermore, decreased protein levels (and activity) of RGS2 have been implicated in the progression of prostate cancer and anxiety." (PMID 25970626, 2015). "In another example, down-regulation of RGS2 expression induces cell proliferation in ovarian cancer, whereas the opposite results occur in prostate cancer." (PMID 37118788, 2023). "The aberrant expression of RGS2 is related to solid tumor development, and RGS2 expression is down-regulated in various cancers, such as ovarian cancer and prostate cancer." (PMID 37649067, 2023). "RGS2 protein expression is reduced in human prostate cancer specimens compared to adjacent normal or hyperplastic tissues, and RGS2 can regulate ERK1/2-mediated androgen-independent androgen receptor (AR) activation." (PMID 37924113, 2023). "Similar phenomena can be also detected in prostate cancer cells, where RGS2 inhibits cell growth with the decreased RGS2 expression while RGS17 enhances cell growth with the increased RGS17 expression." (PMID 37118788, 2023). "In the remaining 25% of patients, alternative mechanisms leading to downregulation of RGS2 gene expression (such as hypoxic cell stress) are likely as it has been described in prostate cancer earlier." (PMID 36230542, 2022). "There have been many reports on the regulation of RGS2 in tumors, and the abnormal expression of RGS2 can be seen in a variety of tumors, such as colon cancer, ovarian cancer, and prostate cancer." (PMID 35992780, 2022). "In prostate cancer, a survival benefit has been reported in patients with low expression of RGS2 similar to observations in pulmonary adenocarcinoma." (PMID 36230542, 2022). "This is consistent with a report by Tu and colleagues that RGS2 is down-regulated in androgen-independent prostate cancer cells, and RGS2 expression suppresses growth in those cells." (PMID 21044322, 2010). "In addition, as a tumor suppressor in several tumors, the expression of RGS2 is low in many cancers, such as breast and prostate cancer." (PMID 33500709, 2021). "Additionally, the RGS2 gene exhibits abnormal expression in prostate cancer." (PMID 39132501, 2024).
ovarian carcinoma (13 papers, 2010 to 2024). A malignant neoplasm originating from the surface ovarian epithelium. "However, the expression of histone H3 in ovarian cancer cells are similar to those in the chemosensitive cells, indicating that the acetylational absence at RGS2 promoter leads to the deficiency of RGS2 expression in ovarian cancer cells with chemoresistance." (PMID 37649067, 2023). "On the other hand, class I HDACs can inhibit the expression of RGS2 in chemically blocked ovarian cancer cells." (PMID 37649067, 2023). "Due to the accumulation of DNA methyltransferase 1 (DNMT1) and class I Histone deacetylases (HDACs) at the RGS2 promoter region, the expression of RGS2 gene is inhibited in ovarian cancer cells." (PMID 37649067, 2023). "In vitro, there is growing evidence that silencing and consecutive suppression of RGS2 leads to chemoresistance in ovarian cancer cells by modulating tumor cell growth." (PMID 36230542, 2022). "Previous studies have reported that the activity of RGS2 is regulated by epigenetic modifications in prostate, testicular, and ovarian cancers 30-32." (PMID 33500709, 2021). "Recently, a study further demonstrates the downregulatiom of RGS2 in drug-resistant ovarian cancer cells partly because Class I HDACs suppress the promoter region of RGS2." (PMID 30064416, 2018). "They discovered that in the regulator of G-protein signaling 2 (RGS2), as an inhibitor of GPCRs, its protein expression is downregulated in ovarian cancer progression." (PMID 29780815, 2018). "While not a major focus of our study, we did observe consistent down-regulation of RGS2 in chemoresistant ovarian cancer cells." (PMID 21044322, 2010). "In addition, the acetylated histone H3 levels at the RGS2 promoter are obviously reduced in chemoresistant ovarian cancer cells, compared with that in chemosensitive cells." (PMID 37649067, 2023). "A relevant study by Cacan showed that loss of histone acetylation at RGS2 promoter genes results in the loss of RGS2 expression and indicated that the downregulation of the RGS2 gene is partly due to accumulation of HDACs at the promoter region of RGS2 in chemoresistant ovarian cancer cells." (PMID 29780815, 2018). "A recent research revealed the modulation of RGS2 expression by DNA methylation and histone deacetylation particularly in the chemoresistant ovarian cancer cells, and as a result, the expression of RGS2 is declined in the ovarian cancer cells resistant to drugs." (PMID 37649067, 2023). "Therefore, to maintain RGS2 repression during ovarian cancer progression, RGS2 promoter might require the accumulation of DNMT1." (PMID 37649067, 2023). "Moreover, RGS2 and RGS10 are found to inhibit cell proliferation in ovarian cancer, whereas RGS19 gives rise to the opposite effect on ovarian cancer progression." (PMID 37118788, 2023). "In addition to RGS2, other RGS proteins such as RGS5, RGS10 and RGS17 are also closely related to ovarian cancer." (PMID 37649067, 2023). "Taken together, these data show that RGS2, RGS10, and RGS17 transcripts are commonly downregulated in acquired chemoresistance in three distinct ovarian cancer cell lines resistant to three distinct chemotherapeutics, while RGS5 was down-regulated in two of the models." (PMID 21044322, 2010).
cardiac hypertrophy (11 papers, 2011 to 2025). "The regulator of G-protein signaling 2 (Rgs2) gene encodes the Rgs2 protein, and its increased abundance is linked with cardiac hypertrophy." (PMID 38611825, 2024). "Interestingly, the authors correlated the accumulation of U-STAT3 in the nucleus to cardiac hypertrophy accompanied by pathogenic gene expression (upregulation of Opn, a marker for heart failure, and downregulation of Rgs2, a negative regulator of cardiac hypertrophy signaling)." (PMID 34440160, 2021). "Recent studies have found that RGS2 expression is significantly downregulated in animal models of renal fibrosis and cardiac hypertrophy, suggesting that RGS2 plays an important role in regulating the pathogenesis of fibrosis." (PMID 36182915, 2022). "A decrease in RGS2 levels is of special interest to this study since it has been shown that such a decrease can result in an exaggerated response to the stress of pressure overload, characterized by hypertrophy and heart failure, in comparison to wild-type controls." (PMID 21829669, 2011). "ISO induced cardiac hypertrophy and interstitial fibrosis in Rgs2/5 dbKO mice without increasing cardiomyocyte size or LV dilation but increased expression of cardiac fetal gene Nppa, α‐actinin, and Ca2+‐/calmodulin‐dependent kinase II." (PMID 39746869, 2025). "Isoproterenol-induced hypertrophy in rat neonatal ventricular cardiomyocytes, via the activation of β-adrenergic receptor (βAR)-Gαs signaling, was accompanied by upregulation of RGS2 mRNA, and RGS2 has been found to have GAP-independent activity in modulating cardiac hypertrophy in this pathway." (PMID 39772618, 2025). "In anti-myocardial hypertrophy, regulators of G-protein signaling (RGS), namely, RGS2 and RGS4, have a central role, leading to cGMP-mediated anti-myocardial hypertrophic effects by inactivating G-protein-coupled signaling, as RGS2 and RGS4 are targets of PKG." (PMID 38186653, 2023).
Anxiety (10 papers, 2009 to 2025). Intense feelings of nervousness, tension, or panic often arise in response to interpersonal stresses. "Qrr1 also shows strong concordance with the orthologous human Chr1 q21–q23 interval, which harbors genes such as Rgs2 (anxiety), Apoa2 (atherosclerosis), and Kcnj10 (seizure susceptibility)." (PMID 41225772, 2025). "RGS2 deficiency in mice leads to an increase in anxiety and decline in male aggression." (PMID 31633064, 2019). "Previous investigations suggest that individuals with depressed Rgs2 levels may be potentially at risk for anxiety- or depressive-like related disorders, which can manifest aggressive behavior." (PMID 31633064, 2019). "Furthermore, extensive human genetic association studies implicate Rgs2 to anxiety, panic, and post-traumatic stress disorders." (PMID 31633064, 2019). "The physiological pathways of anxiety associated with the expression of BDNF, HTR2C, MAOA, and RGS2 can be affected by miR-22 and the repetitive behavior in heterozygous knocked-out mice can be prompted by the partial loss of miR-137." (PMID 36344488, 2022). "The transgenic mouse lines, ePet-Rgs2lo and ePet-Rgs2hi, exogenously expressing RGS2 in the 5HT system were characterized for male anxiety, depression, and aggressive behaviors in comparison to their wild-type littermates." (PMID 31633064, 2019). "Mouse models knocking out Rgs2 show increased anxiety and decreased aggression, and, more recently, heightened neophobia and fear learning." (PMID 31633064, 2019). "RGS2 has been identified as a quantitative trait for anxiety and variations within the Rgs2 gene are expected to play a role for the development of anxiety in humans." (PMID 31633064, 2019). "Likewise, RGS2 is thought to mediate the anxiolytic effects of oxytocin, and affects T cell activation, anxiety, and male aggressive behavior." (PMID 33115496, 2020). "Besides a plethora of data linking changes in 5HT levels to anxiety phenotypes, our data suggest that RGS2 modulates anxiety outside the serotonergic system." (PMID 31633064, 2019). "Furthermore, mice treated with oxytocin demonstrated decreased anxiety with increased RGS2 expression." (PMID 31633064, 2019). "Since the serotonergic system and RGS2 was previously found to be involved in anxiety and aggression in mice, we wanted to investigate whether RGS2 is modulating anxiety and aggression through the serotonergic system." (PMID 31633064, 2019). "Mouse models knocking out Rgs2 (Rgs2−/−) show increased anxiety and decreased male aggression." (PMID 31633064, 2019). "Nonetheless, these data demonstrate that RGS2 may have a protective effect against anxiety and depression, and that RGS2 disruption may have detrimental neuropsychiatric effects." (PMID 30483131, 2018). "Hsa-miR-3591-3p has been found to be downregulated may through regulate RGS2 in anxiety patients." (PMID 30736753, 2019). "In addition, whether RGS proteins such as RGS2 modulate anxiety and aggression via modulating the activity of 5HT neurons have not been explored." (PMID 31633064, 2019). "Furthermore, knock-out mice of Rgs2 show increased anxiety-like behavior." (PMID 23659354, 2013). "Additionally, in the published work, although these mice have been shown to exhibit abnormalities in T-cell activation, anxiety, aggression, and blood pressure, there are no known developmental changes associated with the deficiency of RGS2." (PMID 19262744, 2009). "Together, these results show that rescue of RGS2 in only serotonergic neurons of Rgs2−/− mice is sufficient to recover male aggression but not anxiety, indicating that RGS2 plays a major role in driving male aggression via the serotonergic system." (PMID 31633064, 2019). "They show that exogenous expression of RGS2 in serotogenic neurons augments aggression in male mice and rescues the docile phenotype of Rgs2 knockouts but does not affect anxiety." (PMID 31633064, 2019).
Anxiety (continued). "Here, we found that overexpression of RGS2 in explicitly serotonergic neurons augments male aggression in control mice and rescues male aggression in Rgs2−/− mice, while anxiety is not affected." (PMID 31633064, 2019). "Our data identify a critical neuronal population, that is, serotonergic neurons in the DRN, where RGS2 modulates male aggression but not anxiety." (PMID 31633064, 2019).
asthma (8 papers, 2017 to 2025). "Decreased RGS2 levels are implicated in numerous diseases, including cardiovascular disease and asthma." (PMID 40992661, 2025). "Low RGS2 protein levels are associated with a number of pathologies, including hypertension, heart failure, and asthma." (PMID 40992661, 2025). "This allows effects of Rgs2 deficiency to be explored in an acute neutrophilic setting, and which may be relevant to exacerbations of airway diseases, including asthma." (PMID 30305828, 2018). "Of relevance to therapeutics used in asthma is the finding that RGS2 mRNA is induced in vivo in human airways following budesonide inhalation." (PMID 30305828, 2018). "Single nucleotide polymorphisms in Rgs2, and IRF5 activity have been associated with asthma and our data highlighted upregulated transcription of these genes in HDM-stimulated ILC2s." (PMID 29250067, 2017). "RGS2 knockout mice exhibit increased airway hyperresponsiveness and remodeling in models of asthma." (PMID 39194521, 2024). "The present study therefore supports the clinical use of therapies, such as ICS/LABA combination inhalers, that promote RGS2 expression to improve lung function in acute neutrophilic inflammation, such as exacerbations of asthma or chronic obstructive pulmonary disease." (PMID 30305828, 2018). "Since this enhanced RGS2 expression attenuates increases in intracellular Ca2+ ([Ca2+]i) induced by histamine and methacholine, a beneficial bronchoprotective role for RGS2 in asthma is indicated." (PMID 28107494, 2017). "Since heterotrimeric G-proteins containing Gαq couple to multiple GPCRs (e.g. the histamine H1 receptor, M1/3 muscarinic receptors, leukotriene receptors, or protease-activated receptors (PARs)) that play key roles in asthma pathogenesis, a role for RGS2 as an “anti-asthma” gene is predicted." (PMID 28107494, 2017). "Common asthma therapeutics up-regulate expression of the regulator of G protein signalling (RGS), RGS2." (PMID 30305828, 2018). "While RGS2 is bronchoprotective and its expression may be enhanced by commonly used asthma therapeutics, expression of RGS2 in non-contractile cells suggests additional roles in the airways." (PMID 30305828, 2018).
gastric cancer (8 papers, 2022 to 2024). A primary or metastatic malignant neoplasm involving the stomach. "RGS2 deposition in gastric cancer is associated with increased tumor stage." (PMID 38693916, 2024). "Our results suggest that RGS1 and RGS2 are adverse prognostic factors in some gastric cancer cohorts." (PMID 38693916, 2024). "In gastric cancer, the expression of RGS2 is correlated with the infiltration of 10 types of immune cells." (PMID 39594230, 2024). "High expression of RGS1, RGS2 and RGS3 in patients with gastric cancer has been shown to be associated with poor prognosis or poor tumor stage." (PMID 38693916, 2024). "It is suspected that RGS2 contributes to the initiation and progression of gastric cancer by influencing the migration of immune cells." (PMID 39594230, 2024). "The results of immunohistochemical staining showed that a large amount of RGS2 was deposited in the stroma in gastric cancer." (PMID 36591293, 2022). "High expression levels of RGS2 were detected by Western blot analysis, which indicates a role of RGS2 in the progression of gastric cancer.In gastric cancer, the deposition of RGS2 increased with the increase of clinical stage." (PMID 36591293, 2022). "In order to verify the expression of RGS2 in gastric cancer, we found that RGS2 was expressed to varying degrees in different clinical stages of gastric cancer by immunohistochemical staining, and with the increase of staging, the more RGS2 deposition." (PMID 36591293, 2022). "Here, we analyzed the role of RGS2, in the tumor microenvironment in gastric cancer, and also in other cancer types for the first time." (PMID 36591293, 2022). "Immunofluorescence staining showed that RGS2 was highly expressed in gastric cancer cell lines AGS and MKN45, and most of them were located in the cytoplasm." (PMID 36591293, 2022). "A “core gene”, RGS2 was selected for subsequent experiments, and the relationship between the expression level of RGS2 protein and the prognosis of patients with gastric cancer was evaluated." (PMID 36591293, 2022). "RGS2 was selected as the core gene upon an analysis of the gastric cancer single-cell, and Western blotting and immunofluorescence staining results revealed high level of expression of this gene in gastric cancer cells." (PMID 36591293, 2022). "Accordingly, the expression of RGS2 in gastric cancer cell line was found to be higher than that of GES-1 at both mRNA level and protein level." (PMID 36591293, 2022). "We found that the high expression of RGS2 in gastric cancer was significantly correlated with a shorter survival time." (PMID 36591293, 2022). "Fatty acid metabolism is related to the changes in the immune microenvironment of gastric cancer, and the RGS2 gene may participate in this process by regulating the G protein signaling pathway." (PMID 39132501, 2024). "Coherently, high level of RGS2 was also found in gastric cancer cells, and was closely connected with TIDE, and CD8+ T-cell infiltration in other cancer types, indicating that RGS2 could studied further as a new target for immunotherapy on gastric cancer." (PMID 38274323, 2024). "In gastric cancer, the RGS2 gene is considered a new tumor biomarker." (PMID 39132501, 2024). "Finally, we also discussed the biological significance of the RGS2 gene in multiple cancer types to fully understand the role of fatty acid metabolism in gastric cancer, and to provide a theoretical basis for effective treatment." (PMID 36591293, 2022). "RGS2 may thus be studied further as a new target for immunotherapy in future studies on gastric cancer." (PMID 36591293, 2022). "Therefore, we speculate that RGS2 participates in the occurrence and development of gastric cancer by affecting the migration of immune cells." (PMID 36591293, 2022). "RGS2, GJA1, GPX3, and LOX were less expressed in gastric cancer tissues than in paracancerous tissues (P<0.05)." (PMID 39132501, 2024).
gastric cancer (continued). "PELI2, RGS2 and ENO2 has been poorly reported in relation to liver cancer, whereas PELI2 involved in 28 gene expression characteristics can well predict gastric cancer with lymphatic metastasis." (PMID 37397026, 2023). "We have determined the mRNA and protein expression levels of RGS2 in GES-1 gastric mucosal cells and AGS, HGC-27, MKN-1, and MKN-45 gastric cancer cell lines." (PMID 36591293, 2022). "Therefore, in the microenvironment of gastric cancer, RGS2 may predict a poor prognosis." (PMID 36591293, 2022). "Finally, we carried out qRT-PCR analysis of the expression levels of RGS2, GNAI2, ANXA5, MARCKS, CD36, NRP1, and PDE4A in gastric cancer cells." (PMID 38274323, 2024).